PLEKHA5 (pleckstrin homology domain containing A5)
Diseases named in the same sentence as PLEKHA5 in open-access papers (continued):
Sharing a sentence is not in itself a finding about the gene and the disease.
tumor (continued). "The detection of markers suchas PLEKHA5 and NDRG1 in primary tumour biopsies could provide an earlyindication of aggressive phenotype, providing they can be fully validated.Practical limitations on prognostic biomarker translation are expertly reviewedelsewhere." (PMID 35225863, 2022). "Notably, the depletion of Plekha5/PLEKHA5 in mouse and human cells had no obvious effect on tumor growth." (PMID 32978388, 2020).
cancer (7 papers, 2020 to 2025). A tumor composed of atypical neoplastic, often pleomorphic cells that invade other tissues. "PLEKHA5 has been extensively implicated in tumorigenesis and cancer progression through context-dependent mechanisms." (PMID 40356756, 2025). "Here, the authors analyze SNVs and CNVs simultaneously in bulk and single cells of BRCA1-associated breast tissues and cancers and show that Plekha5 deficiency promotes metastasis." (PMID 32978388, 2020). "Among the downregulated DEGs, PLEKHA5, GRK4, MYRIP, and CD40 have established associations with various human cancers." (PMID 39911484, 2024). "The detailed analysis of the mechanism and importance of PLEKHA5 phosphorylation in Met signaling are critical for evaluating PLEKHA5 as a therapeutic target and a biomarker for Met-addicted carcinoma." (PMID 33677467, 2021). "Considering that PLEKHA5 is widely expressed in cancer cell lines 37 and in this study, PLEKHA5 may also act downstream of oncogenic molecules besides Met and may have other cellular functions in some contexts." (PMID 33677467, 2021). "Our findings may provide a novel approach for molecular targeted therapy targeting PLEKHA5 in patients with Met-addicted carcinoma." (PMID 33677467, 2021). "Considering that PLEKHA5 silencing had a negligible effect on the growth of normal cells, blocking PLEKHA5 function may have therapeutic potential against Met-addicted carcinomas with minimal side effects." (PMID 33677467, 2021). "In addition, PLEKHA5 silencing selectively suppressed the growth of carcinoma cells with Met gene amplification." (PMID 33677467, 2021). "Thus, PLEKHA5 phosphorylation could be a biomarker for Met-addicted carcinoma." (PMID 33677467, 2021).
infection (1 paper, 2018). The state of being infected such as from the introduction of a foreign agent such as serum, vaccine, antigenic substance or organism. "The results suggested that multiple plasma membrane proteins may be degraded during infection, in particular proteins that include a pleckstrin homology (PLEKH) domain (for example PLEKHA5) or that function in cell-to-cell adhesion." (PMID 30122656, 2018).
PLEKHA5 also shares sentences with these, for which no sentence is quoted: calculus (1 paper); cerebral tumors (1); ependymoma (1); hepatocellular carcinoma (1); Macrocephaly (1); myocardial infarction (1); of puberty (1); oral diseases (1); Parkinson disease (1); periodontal diseases (1).